IL1B (interleukin 1 beta)
Diseases named in the same sentence as IL1B in open-access papers (continued):
Sharing a sentence is not in itself a finding about the gene and the disease.
Hepatic steatosis (continued). "In a high-fat diet-induced mouse model of fatty liver disease, the release of interleukin-1 beta (IL-1β) by KCs promotes hepatic steatosis by inhibiting peroxisome proliferator-activated receptor alpha (PPARα) activity in hepatocytes." (PMID 38147020, 2023). "Meanwhile, hepatic macrophages promoted hepatic steatosis via IL1β-dependent suppression of Pparɑ activity." (PMID 37063432, 2023). "Pro-inflammatory cytokines IL-1β induce hepatic steatosis, aggravate the inflammatory reaction, and further promote the occurrence and development of NAFLD." (PMID 36432531, 2022). "In mice with diet induced NASH l, FASNi prevented development of hepatic steatosis and fibrosis, and reduced circulating IL-1β." (PMID 36123383, 2022). "IL-1β is involved in the metabolic activity of different acute liver injury symptoms and promotes hepatic steatosis." (PMID 35399623, 2022). "IL-1β promotes hepatic steatosis by stimulating triglyceride and cholesterol accumulation in primary liver hepatocytes and inducing lipid droplet formation." (PMID 33525359, 2021). "In an HFD-induced murine fatty liver disease, IL-1β released from KCs promotes hepatic steatosis by inhibiting PPARα activity in hepatocytes." (PMID 34956171, 2021). "HFD induced significant hepatic steatosis as assessed by hematoxylin and eosin staining as well as inflammation indicated by significantly increased hepatic expression of IL-1β and TGFβ at both the transcript and protein levels." (PMID 33525359, 2021). "In C57BL/6 mice with fatty liver disease, steatosis promotes the secretion of IL-1β, which is beneficial for M1-like macrophage polarization, whereas in BALB/c mice, steatosis mainly induces M2-like macrophage responses." (PMID 34956171, 2021). "Hepatic macrophages participate in the development of fatty liver disease by secreting multiple pro-inflammatory cytokines, including IL-1β, IL-6, and TNF-α." (PMID 34956171, 2021). "Casp-1 and ASC, as well as inflammasome complexes, have been found as master regulators of IL-1β activation or signaling, which is required for the development of liver steatosis, inflammation, and damage." (PMID 33265944, 2020). "IL-1β promotes liver steatosis, inflammation and fibrosis via activation of the IL-1 receptor (IL-1R) signaling." (PMID 31921154, 2019). "IL-1β stimulates TG and cholesterol accumulation in hepatocytes and as such contributes to the development of hepatic steatosis." (PMID 31921154, 2019). "In mice, IL-1β was found to promote hepatic steatosis by stimulating triglycerides, cholesterol accumulation, and lipid droplet formation and to regulate inflammation, hepatic insulin resistance, and fibrosis." (PMID 31736870, 2019). "ACR and ARB reduced the hepatic expression levels of Tnfa, Il6, and Il1b mRNA in OLETF rats with improved hepatic steatosis." (PMID 30477453, 2018). "IL-1β signaling is required for development of alcohol-induced liver steatosis, inflammation, and injury, attributed to inflammasome activation in bone marrow-derived Kupffer cells." (PMID 28729463, 2017). "The subsequent decrease in IL-1β production in hepatocytes contributes to alleviating hepatic steatosis." (PMID 27075683, 2016). "Taken together, our findings suggest that ER stress-induced inflammasome activation and IL-1β production generate a positive feedback loop to amplify inflammatory response, eventually leading to liver steatosis and injury." (PMID 27942420, 2016). "To further define the role of inflammasomes and IL-1β in ER stress-induced hepatic steatosis, we utilized a Tunicamycin (TM)-induced steatosis animal model." (PMID 27942420, 2016). "Although this and other studies indicate the involvement of inflammasome and IL-1β in liver injury and steatosis, the cellular source and targeting cells of IL-1β in hepatic steatosis are less clear." (PMID 27942420, 2016).
Hepatic steatosis (continued). "IL-1β promotes hepatic steatosis by activating PPARα and diacylglycerol acyltransferase 2, an enzyme that converts diglyceride to triglyceride." (PMID 21274430, 2010). "Chitin oligosaccharides can increase SCFAs content, reduce serum LPS, improve blood lipid profiles and liver steatosis, decrease the levels of inflammatory factors such as IL-1β, IL-6, and TNF-α to alleviate inflammation, and promote mRNA expression of TJPs to enhance the integrity of the IMB." (PMID 40862134, 2025). "For example, IL-1β might promote TGs and cholesterol accumulation and the development of lipid droplets in hepatocytes, thus promoting hepatic steatosis." (PMID 39859279, 2025). "Notably, the combined drug regimen treats hepatic steatosis by inhibiting the IL-1β and α-SMA pathways in NAFLD." (PMID 38595921, 2024). "Additionally, it was shown that IL-1β, which is extensively expressed in the many subpopulations of liver cells, has a significant role in liver illness, including hepatic steatosis, inflammation, and fibrosis." (PMID 37173727, 2023). "In addition, there were statistically significant positive correlations (p < 0.001; r = 0.42) between hepatic steatosis and the concentration of IL-1β in saliva." (PMID 36769216, 2023). "We also reported how feeding SPI reduces the expression of inflammation-related genes, such as IL-33 and IL-1B, that could be helping in the general reduction of liver steatosis observed with the SPI diet." (PMID 34262928, 2021). "In mice with fatty liver disease, KCs are a major source of IL-1β." (PMID 34956171, 2021). "While IL-1α and IL-1β play a pivotal role in inflammation and inflammatory diseases, including hepatic steatosis, other members of this family may hold anti-inflammatory or pro-inflammatory functions during liver inflammation and steatosis." (PMID 27942420, 2016). "Complementarily, IL-1β knockout mice were more insulin sensitive on either normal chow or high fat diet, and both IL-1β and IL-1α knockouts were protected against hepatic steatosis induced by high fat or atherogenic diets." (PMID 23341960, 2013). "Furthermore, in other studies, IL1-R1 and IL-1β knockout mice display attenuated hepatic steatosis and inflammation when exposed to alcohol and high cholesterol diet." (PMID 24146946, 2013). "Since IL-1β is at least partially involved in the development of hepatic steatosis, it may also play a considerable role in maintaining increased hepatic triglyceride concentration in arthritic rats on high-fat diet." (PMID 20953376, 2010). "Consistently, excessive lipid accumulation could further promote TLR4/NF‐κB signaling to trigger the leakage of proinflammatory cytokines (TNF‐α, IL‐6, IL‐1β, and IL‐18), thus exacerbating the vicious cycle of inflammatory responses in the liver to aggravate fatty liver progression." (PMID 40501499, 2025). "Additionally, IL-1β may encourage hepatic steatosis by promoting the accumulation of triglycerides and cholesterol in primary liver hepatocytes as well as the development of lipid droplets." (PMID 37173727, 2023). "In addition, the secretion of IL-1β from Kupffer cells enhances lipid accumulation in a NASH model induced by choline-deficient amino acid-defined (CDAA) diet, while IL-1R−/− mice exhibited reduced hepatic steatosis." (PMID 35078487, 2022). "And the associations of CRP, IL-1β, and IL-6 with hepatic steatosis were not significant." (PMID 35603224, 2022). "Moreover, IL-1β promotes hepatic stellate cells (HSCs) activation, resulting in liver fibrosis, as well as enhances the accumulation of triglyceride and hepatocyte injury contributing to liver steatosis." (PMID 36160411, 2022). "It has been clearly demonstrated that saturated, but not unsaturated, free fatty acid (FFA), which is a host-derived metabolite, is capable of activating the NLRP3 inflammasome to produce IL-1β and that this IL-1β might lead to progression to NASH in mice with simple hepatic steatosis." (PMID 26549942, 2015).
Hepatic steatosis (continued). "The levels of pro-inflammatory markers, such as IL-6, IL-1β, and TNF-α, were significantly reduced after EA administration, confirming the compound's ability to mitigate hepatic steatosis and inflammation in a dose-responsive manner." (PMID 41530836, 2026). "Compared with HFHC, both CAB and HECAB reduced serum insulin and HOMA-IR, attenuated hepatic steatosis, increased SOD1 and CAT, and reduced NF-κB, IL-6, TNF-α, and IL-1β, whereas GPx1 remained unchanged." (PMID 42193214, 2026). "As expected, overexpression of NRF2 improved liver steatosis in diet‐induced obese mice, while inhibiting pyroptosis and inflammation markers, including cle‐Caspase1, GSDMD, N‐GSDMD, Pro‐IL1β and IL1β." (PMID 39995148, 2025). "In ALD cases, hepatic steatosis can lead to concomitant changes in the gene expression levels of proinflammatory factors such as TNF-α, IL-6, and IL-1β." (PMID 38999886, 2024). "Knockout of miR-34a in HFD-fed obese mice attenuated VAT fibrosis, local (WAT CLS formation/M1 polarization) and systemic (serum cytokines: TNF-α, IL-6, IL-1β, and MCP-1) metaflammation, insulin resistance, and hepatic steatosis." (PMID 39063184, 2024). "Cichoric acid plays an important role in reducing hepatic steatosis, as it reduces the expression of lipogenic actors, such as SREBP-1c, DGAT1, FAS, and SCD-1, and also of inflammatory factors such as IL-6, IL-1b, NF-κB, and TNF-α." (PMID 39458995, 2024). "Statistically significant, positive correlations between hepatic steatosis and the concentration of MMP-2 (matrix metalloproteinase 2), resistin, and IL-1β in saliva were also found." (PMID 36769216, 2023). "Here, we provide solid evidence that celecoxib reduces lipogenesis‐triggered hepatic steatosis in AKT‐transfected mice, accompanied by the suppression of hepatocellular inflammatory responses (TNF‐α, IL‐6 and IL‐1β)." (PMID 35713152, 2022). "Consistent with the lower ALT levels, less hepatic steatosis, and higher AMPK activity, POA treatment reduced hepatic levels of the pro-inflammatory cytokines MCP-1 and TNF-α compared with OA treatment, while IL-1β remained unchanged." (PMID 32738301, 2020). "The levels of IL-1β and TGF-β1 were higher in the hepatic steatosis groups than those in the control group." (PMID 32526845, 2020). "Mechanistic studies found that herbal formula such as shenling baizhu powder alleviated hepatic steatosis and repaired colon mucosa via decreasing the expression level of endotoxin and inflammatory mediators (TNF-α, IL-1β) via the TLR4 pathway." (PMID 32477116, 2020). "Elafin overexpression inhibited liver steatosis in the HFD-treated male mice 5,38, which was reversed by injection of IL-1β or IFNγ protein." (PMID 32733043, 2020). "Flaxseed oil rich in ALA intervention apparently decreased the serum level of inflammatory cytokines (IL-6, IL-1β, MCP-1, and TNF-α) and attenuated hepatic steatosis by regulating ER stress." (PMID 33273997, 2019). "TNF-α and IL-1β, pro-inflammatory and lipogenic factors, play crucial roles in the pathogenesis of NAFLD/NASH (liver steatosis, necrosis, apoptosis and fibrosis)." (PMID 27483220, 2016). "In the current study, exacerbated hepatic steatosis in MOT group was evidenced by an elevated hepatic immunophenotype which included upregulated TNF-α and IL-1β expression." (PMID 24146946, 2013). "The MAS score and levels of pro-inflammatory markers, including IL-6, IL-1β, and TNF-α, were significantly decreased following EA administration, demonstrating the compound's efficacy in attenuating hepatic steatosis and inflammation in a dose-responsive manner." (PMID 41530836, 2026). "This inhibition leads to downregulation of mRNA levels of SIRT6 target genes ACC1, SCD1, FAS, and CRFVL6, and reduced serum inflammatory factors TNF-α, IL-1β, IL-4, IL-6, IL-2, and chemokine MCP-1, which in turn attenuates hepatic steatosis and inflammation in HFD mice." (PMID 40292292, 2025).
Hepatic steatosis (continued). "In addition, overexpressing IREB2 increased IL-1β, IL-6, and TNF-α, promoting HFD-induced metabolic disorders, hepatic steatosis, and inflammation." (PMID 39910919, 2025). "However, IL-1β had 42.7% sensitivity and 93.55 specificity in discriminating between early and late post-MAFLD hepatic steatosis, with a significant p-value." (PMID 39179677, 2024). "Other studies also reported elevation of IL-6, but not TNFα and IL-1β, as a compensatory mechanism that prevents the development of hepatic steatosis at the early stage of NAFLD." (PMID 38590904, 2024). "Recently, experimental research revealed the mechanism underlying Dansheng Zexie decoction in treating NAFLD, which reduces lipid accumulation and alleviates hepatic steatosis, oxidative stress, and inflammation via inhibiting the ROS/NLRP3/IL-1β signaling pathway." (PMID 36160411, 2022). "In CDAA diet-induced murine steatohepatitis, TLR9 knockout relieves hepatic steatosis, inflammation, and fibrosis by suppressing IL-1β secreted by KCs rather than hepatocytes and hepatic stellate cells." (PMID 34956171, 2021). "Furthermore, hepatic steatosis and levels of TNF-α, IL-6, IL-1β inflammatory genes increased in OVX rats, but were reduced after BCE intake." (PMID 32466275, 2020). "A previous report found that a similar phenotype of liver steatosis did not induce significant changes in inflammatory mediators, such as Il-6, Tnf-α, or Il-1β." (PMID 33391254, 2020). "Therefore, the preventive effect of curcumin on hepatic steatosis is mediated, at least in part, by inhibiting hepatic TLR4-MyD88/NF-κB pathway and the subsequent production of TNF-α and IL-1β." (PMID 31788011, 2019). "Moreover, dietary genistein had the potential to directly alleviate the inflammatory response by modulating the expression of inflammatory factors such as NF-кB, IL-8, IL-1β, and IFN-γ through the involvement of PPARδ and T-cell factor 3 (TCF3) in laying hens induced fatty liver." (PMID 38540097, 2024). "Since it has been reported that fatty liver can promote inflammation, which is a key player in progression of both alcoholic and non-alcoholic liver diseases, we examined the expression of inflammatory markers, monocyte chemoattractant protein 1 (MCP-1), and interleukin 1 beta (IL-1β)." (PMID 33746771, 2021). "Clinical studies examining patients with hepatic steatosis or NASH found supplementation, twice daily, with L-TRP for 14 months result in decreased plasma LDL, TG, and gamma gluthamylo transpeptidase levels with a correlative decrease in plasma IL-1β, IL-6, and TNF." (PMID 31921154, 2019). "Our findings demonstrate that inflammatory and metabolic stress pathways, including TNF, IL-6, IL-1β, and MAPK13 signaling, promote the progression of hepatic steatosis to MASH and fibrosis under KD at TN but not at RT." (PMID 40864559, 2025). "In addition, we also found that the mRNA levels of hepatic proinflammatory cytokines such as IL-6 and IL-1β were significantly downregulated in VPA group relative to control group S2 Fig, suggesting that VPA-caused liver steatosis and oxidative stress might not be associated with the inflammation." (PMID 37971986, 2023). "Our results showed that the expression of AIM2 is positively correlated with IL-1β and IL-18 expression in CHB patients and not correlated in the control fatty liver disease patient group." (PMID 26290184, 2015). "With selective depletion of KCs in the ob/ob mouse, our data suggests that this improvement in hepatic steatosis is independent of VATM depletion, and that KCs and KC-derived cytokines, including IL-1β are important for hepatic metabolism regulation." (PMID 25216251, 2014).
peritonitis (132 papers, 2010 to 2025). Inflammation of the peritoneum (tissue that lines the abdominal wall and covers most of the organs in the abdomen). "Mainly, high IL-1β and IL-6 serum levels are associated with a high mortality risk in acute peritonitis." (PMID 39531431, 2024). "We evaluated pro-inflammatory cytokine levels before and after PD-associated peritonitis; interestingly, the levels of IL-1β remained high in the PD fluid, even after remission of bacterial peritonitis." (PMID 38114999, 2023). "PTPN22 deficiency prevents MSU-induced peritonitis in mice by inhibition of inflammasome-dependent IL-1β production." (PMID 29868015, 2018). "Moreover, NLRP3 activation and IL-1β release are critical for solute transport defects and tissue remodeling in PD-associated peritonitis." (PMID 38114999, 2023). "Interestingly, if the peritonitis caused by the resistant strains of P. aeruginosa, Epinecidin-1 treatment significantly increased plasma concentrations of IL-1β and TNF-α." (PMID 31138331, 2019). "Previous studies have shown that BjV causes leukocyte infiltration with the predominance of neutrophils in mice muscle tissue, neutrophil migration in peritonitis, and increased levels of IL-6 and IL-1β in the peritoneal cavity." (PMID 40864043, 2025). "Our results revealed that baicalin can decrease the protein expressions of TNF-α, IL-1β, and IL-6 in GPS-infected PPMCs and piglets, which suggests that the regulation of inflammatory injury is helpful in alleviating peritonitis caused by GPS." (PMID 40867785, 2025). "To examine NLRP3 inhibition in vivo, we performed a well-characterized model of peritonitis using i.p. injection of LPS followed by ATP, where IL-1β production in the peritoneal cavity is NLRP3 dependent." (PMID 40892070, 2025). "In particular, USP13 ablation in mice attenuated MSU-induced peritonitis, as manifested by decreased IL-1β release and inflammatory cell infiltration." (PMID 41004574, 2025). "Oral administration of LPE has been shown to attenuate peritonitis by reducing pro-inflammatory mediators (IL-1β, IL-6, and TNF-α) and increasing IL-10 secretion." (PMID 40079578, 2025). "DW18134 significantly reduced the LPS-stimulated expression of Tnfa, Il6, and Il1b in peritonitis mice livers; the effect showed good dose dependence at 15 mg/kg and 30 mg/kg." (PMID 38675622, 2024). "In vitro, SERTAD1 knockout was associated with decreased IL-1β and IL-18 secretion, while in vivo loss of SERTAD1 attenuated peritonitis and experimental autoimmune encephalomyelitis (EAE)." (PMID 38763335, 2024). "The levels of the pro-inflammatory cytokine IL-1β increased by 213.6% (p < 0.001) in the peritoneal lavage of the peritonitis group compared to the naive group." (PMID 39452085, 2024). "Pellino-1 knockout mice were resistant to alum-induced peritonitis, with increased survival and decreased serum IL-1β." (PMID 38763335, 2024). "Pro-inflammatory cytokines were elevated after 24 h of peritonitis formation, especially IL-1Ra, IL-1b, IL-6, IL-8, and TNF-α." (PMID 38087374, 2023). "This first case report suggests that an increased interleukin-1β (IL-1β) expression in the peritoneal dialysate after healing of peritonitis can contribute to peritoneal deterioration." (PMID 38114999, 2023). "Peritonitis promotes peritoneal fibrosis through inflammatory factors such as IL-1β and IL-6, exacerbating the chronic induction of TGF-β1 synthesis, and promoting fibrosis events." (PMID 37817984, 2023). "We used an acute peritonitis model induced by intraperitoneal (i.p.)injection of IL-1β and quantified neutrophil migration within the extravascular space in WT and Pecam1-/- mice by flow cytometry." (PMID 37549051, 2023). "The intraperitoneal injection of MSU leads to NLRP3 inflammasome-dependent peritonitis, which is characterized by IL-1β and IL-18 production and the neutrophil influx into the peritoneal cavity." (PMID 36975504, 2023).